ST3GAL1 (ST3 beta-galactoside alpha-2,3-sialyltransferase 1)
Diseases named in the same sentence as ST3GAL1 in open-access papers (continued):
Sharing a sentence is not in itself a finding about the gene and the disease.
cancer (37 papers, 2009 to 2026). A tumor composed of atypical neoplastic, often pleomorphic cells that invade other tissues. "Although ST6Gal-1 is known as the main player in sialic-acid-related cancer progression and therapeutic resistance, sialyltransferase ST3Gal1 has also been linked to cancer progression and drug resistance." (PMID 37894470, 2023). "While the T and ST antigens are found on normal O-glycans such as in hematopoietic cells, ST3Gal1 overexpression is found in different types of malignancies, and has been linked to poor prognosis." (PMID 34975914, 2021). "ST3GAL1 is mainly associated with O-linked sialylation in cancer cells, whereas ST3GAL4 is mainly associated with N-linked sialylation." (PMID 30375371, 2018). "ST3GAL1 is a sialyltransferase that catalyzes the transfer of sialic acid from cytidine monophosphate-sialic acid to galactose-containing substrates and is associated with cancer progression and chemoresistance." (PMID 30375371, 2018). "Specifically, related to this pathway, we observed down-regulation of genes such as b4galt3, st3gal1, and a notable 5-fold increase in b3gnt7 expression, a combination that is consistent with current metastasis literature in many cancer types." (PMID 40719625, 2025). "Aberrant expression of ST3GAL1 and ST3GAL3 was found in different cancer types and has been associated poor prognosis and cancer progression." (PMID 38274327, 2024). "ST antigens were also elevated in cancer, and the silencing of ST3GAL1 significantly reduced the level of these antigens, further reducing the tumor size in the prostate cancer xenograft mouse model." (PMID 37372117, 2023). "In cancer, the aberrant sialylation is closely related to elevated expression of sialyltransferases, including ST3Gal1, STGal4, ST6-Gal1 and ST8Sia2, and their products, especially Sialyl-Levisa,x epitopes that correlate with poor prognosis." (PMID 33670244, 2021). "One of the first evidence that the ST3GAL family is involved in cancer came from the finding that ST3GAL1 overexpression promotes mammary tumorigenesis, although the mechanism by which this ST exerts its oncogenic function was not elucidated." (PMID 33921986, 2021). "The β-galactoside-α-2,3-sialyltransferase-1 ST3GAL1 catalyzes the transfer of sialic acid from cytidine monosphosphate (CMP)-sialic acid to galactose-containing substrates and is associated with cancer progression and drug resistance." (PMID 33203881, 2020). "There was a significant difference in the level of ST3GAL1 expression between the three cancer cell lines with the highest expression in SKOV-3 cells and the second highest in OVCAR3 cells." (PMID 30375371, 2018). "ST3GAL1, up-regulated by cadmium exposure, is differentially expressed in several types of cancer including bladder, ovarian, breast, and colorectal." (PMID 21457566, 2011). "The results showed that CERS2, VAPB, GPAA1, and ST3GAL1 were widespread CNVs in pan-cancer." (PMID 36059802, 2022). "Among them, ST3GAL1 is the most reported in various cancer types, including BC." (PMID 35444644, 2022). "The beta-galactoside alpha-2,3-sialyltransferase 1 (ST3Gal1) is upregulated in cancer and thus it is central to a strategy focused on the synthesis of inhibitors against hypersialylation of proteins and lipids to prevent metastasis and overcome resistance to chemotherapy." (PMID 31784620, 2019). "In addition, we found that the expression of ST3GAL1 could vary significantly in different ovarian histological cell types and there was a significantly higher expression of ST3GAL1 in more severe grades of cancer." (PMID 30375371, 2018). "Importantly, overexpression of the hypoglycosylated STn- and ST-MUC1 forms, induced by transfection with glycosyltransferases ST6GalNAc1 and ST3Gal1 encoding plasmids, enhanced its interaction with CIN85 and increased the migratory and invasive activities of cancer cells." (PMID 27754373, 2016).
cancer (continued). "It is clear from the presented literature that ST3GAL1 and ST6GAL1 are the most extensively studied sialyltransferases in cancer." (PMID 33921986, 2021). "We have conducted an integrated analysis of genomic, epigenomic, and transcriptomic data to estimate how the key SA genes, namely CMAS, ST3GAL1, ST3GAL5, and NEU1, are regulated across different cancer types." (PMID 32296639, 2020). "High ST3GAL1 expression and T/sT replacement in BCG challenged-BC cancer cells induce a stronger macrophage response and alter the gene expression towards genomic instability, indicating a potential impact on BC biology and patient’s response to BCG." (PMID 29454317, 2018). "In addition, cancer histological type may influence the expression of ST3GAL1." (PMID 30375371, 2018). "Twenty of these genes are located in 8q22–q24 and 17q21, including PAPBC1, RAD21, ATAD2, MTSS1, SQLE, ST3GAL1, C17orf37, ABCC3 and PTPN2, previously reported as cancer-related genes." (PMID 21339811, 2011). "The α-2,3-sialyltransferase ST3GAL1 was also observed in many cell types; however, it was not enriched in cancer-specific ductal cells." (PMID 34634466, 2021).
infection (8 papers, 2015 to 2025). The state of being infected such as from the introduction of a foreign agent such as serum, vaccine, antigenic substance or organism. "Similarly, at day 7 PI, infection caused a significant decrease of St3Gal4, while St6GalNAc1, St6Gal1, and St3Gal1 showed a trend toward reduction." (PMID 39412866, 2024). "ST3GAL1 gene variants may be related to a higher or lower expression of the receptor on the surface of pneumocytes and thus interfere with the capacity of infection of the Influenza A(H1N1)pdm09 virus in cells of the lower respiratory tract, contributing to complications of this disease." (PMID 26436774, 2015). "Infection/inflammation increases ST3GAL1 and epithelial sialylation in vivo, indicating context-responsive control relevant to mucin termini." (PMID 41301470, 2025). "Combining in vitro and in vivo approaches, we show that miR-125a-5p regulates the expression of the sialyltransferase ST3GAL1 in an infection-dependent manner." (PMID 37848994, 2023). "While miR-125a-5p was significantly downregulated by 0.6-fold (P ≤ 0.0001), a pronounced upregulation of St3gal1 gene expression was observed after infection (> 4-fold; P ≤ 0.0001)." (PMID 37848994, 2023). "Enhanced HU02Av−H5 infection of HEKΔSiaN cells upon transfection by ST3Gal1 (15% of WT) or ST3Gal2 (30% of WT) was unexpectedly observed which suggests that ST3Gal1 and 2 may indeed use type II LN substrates on N-glycans." (PMID 40487452, 2025). "Compared to mock-infected cells, AIV infection significantly upregulated the expression of ST3GAL6 and MGAT2 genes at 12-, 24-, 36-, and 48-hours post-infection, and ST3GAL1 gene at 24-, 36-, and 48-hours post-infection, while B4GALT1 expression remained largely unchanged." (PMID 39652582, 2024). "Following the interaction and gene expression analysis, the aim was to verify whether the infection-dependent downregulation of miR-125a-5p exerts an effect on the protein concentration and distribution of ST3GAL1 in colonic tissue." (PMID 37848994, 2023). "The results of the in vivo experiments suggested that the mRNA level of ST3GAL2 might be modulated by miR-615-3p and miR-125a-5p may play a regulatory role on ST3GAL1 transcription in colonic tissue after C. jejuni 81–176 infection." (PMID 34183045, 2021). "We showed that genetically engineered chicken DF-1 cells overexpressing both TMPRSS2 and ST3GAL1 support infection and replication of influenza virus in the absence of trypsin." (PMID 33413322, 2021).
ST3GAL1 also shares sentences with these, for which no sentence is quoted: glioblastoma (3 papers); ovarian serous carcinoma (2); adenocarcinoma (1); bacterial infections (1); basal cell carcinoma (1); bladder tumors (1); breast tumor (1); CNS tumors (1); COVID-19 (1); endometrial cancer (1); endometrioid ovarian cancer (1); Fanconi anemia (1); Fibroadenoma (1); hematological malignancies (1); hepatocellular carcinoma (1); keratoacanthoma (1); lymph node metastasis (1); metabolic disorders (1); myeloma (1); neurological diseases (1); osteoporosis (1); postmenopausal osteoporosis (1); prostate adenocarcinoma (1); Sepsis (1); skin cancer (1); squamous cell carcinoma (1); squamous cell carcinoma of the cervix (1); theileriasis (1).